ANXA1 (annexin A1)
Diseases named in the same sentence as ANXA1 in open-access papers (continued):
Sharing a sentence is not in itself a finding about the gene and the disease.
cancer (continued). "Furthermore, this ANXA1 overexpression depending on the cancer proliferation status suggests the potency of ANXA1 as a biomarker of the identification of cancer, aiding in the identification of cancer early." (PMID 32226026, 2020). "In our study, we found that ANXA1 was overexpressed in the PBMCs of cancer patients, and thus hypothesized that it could serve as a biomarker of cancer diagnosis." (PMID 32226026, 2020). "Another membrane-bound protein ANXA1 was reported to be involved in the cancer development as well." (PMID 32351780, 2020). "Because of its abnormal expression in PBMCs, ANXA1 might be a meaningful biomarker for cancer diagnosis and is considered a primary mediator of anti-inflammatory activity." (PMID 32226026, 2020). "Additionally, the identification of ANXA1 as a circulating molecule in the sera of cancer-affected patients has been considered as prognostic factor because of its correlation with clinicopathological conditions." (PMID 33353163, 2020). "As expected, ANXA1 plays multiple roles in cancer progression similar to MITF." (PMID 33293474, 2020). "Many published papers on anxA1 expression in cancer report the use of either polyclonal antibodies, which have high liability for cross-reaction with other annexins, or antibodies such as clone 29, which was shown in our study to recognize the cleavable anxA1 N-terminal domain." (PMID 32497150, 2020). "Similarly, cancer cells undergoing ICD release the cytoplasmic protein annexin A1 (ANXA1), another DAMP that binds to formyl peptide receptor 1 (FPR1) at the surface of DCs." (PMID 33281620, 2020). "It follows that inhibiting the activation of FPR1 by ANXA1, may have a potential role as a therapy against a number of cancers." (PMID 33057069, 2020). "In addition to the primary immunodeficiency pathway, a large proportion of the summarized genes, including ANXA1, are involved in the cytokine-cytokine receptor interaction reference pathway that affects the status of carcinoma." (PMID 32226026, 2020). "Nevertheless, it is now accepted that ANXA1 has extensive effects beyond the immune system with consequences in preserving homeostatic secretion, fetal development, the aging process, and development of several diseases such as cancer." (PMID 31970082, 2019). "Given the previous reports that demonstrated the role of ANXA1 in the attraction of several immune cells to cancer in animal models, we investigated whether this was the case in human primary TNBC utilizing the CIBERSORT algorithm in TCGA and METABRIC cohorts." (PMID 31461932, 2019). "This was a novel role for the ANXA1/PI3K/AKT pathway in cancer biology." (PMID 31882967, 2019). "It has been demonstrated that protein annexin A1, A2, A4 and A5 play an important role in the occurrence and development of these two cancer types, and BRCA1 and BRCA2 gene mutations are commonly observed in both cancer types." (PMID 31405076, 2019). "One of the proteins upregulated in liver metastatic ECM, annexin A1, was not previously studied in the context of cancer-associated matrisome." (PMID 31545917, 2019). "Annexin A1 knockdown inhibits proliferation and promotes migration of cancer cells." (PMID 31545917, 2019). "In different cancers ANXA1 expressions are either up regulated or down regulated." (PMID 31777500, 2019). "Notably, two forms of annexin with antagonistic effects during cancer progression were identified: annexin A1, which inhibits antiapoptotic signaling pathways, and annexin A2, which promotes cancer cell proliferation." (PMID 31382537, 2019). "Further studies are required to evaluate the effectiveness of targeting ANXA1 for cancer therapies." (PMID 29614751, 2018). "ANXA1 that translocates to the cell membrane interacts with formyl peptide receptors (FPRs) and is involved in inflammation, neuroendocrine system regulation, skeletal muscle differentiation, and cancer progression." (PMID 30364320, 2018).
cancer (continued). "Thus, ANXA1 represents a possible target for novel therapies and/or a potential biomarker for cancer diagnosis and screening." (PMID 29986379, 2018). "Moreover, considerable evidence has indicated that Annexin A1 deregulation is involved in the development, invasion, metastasis, and progression of a variety of cancers." (PMID 28355254, 2017). "We previously demonstrated that both non-steroidal and steroidal anti-inflammatory drugs such as glucocorticoids and nitric oxide–aspirin, induce expression of ANXA1, which directly binds to the NF-κB p65 subunit, and thereby inhibits its activation in cancer models." (PMID 28912778, 2017). "Since it has been amply demonstrated that ANXA1 is a functional target of miR-196a in various cancers including HNSCC15, 25, 26, it remained necessary to determine the specificity and causal relationship between annexin A1 mRNA and protein levels with miR-196a and miR-196b expression." (PMID 28754915, 2017). "Whether the effect of ANXA1 on NF-κB or other signalling molecules are related to cancer tissue specificity remains to be established." (PMID 29263330, 2017). "Besides the inflammatory effects, ANXA1 also plays essential roles in cell proliferation, differentiation, apoptosis and cancer." (PMID 29233185, 2017). "ANXA1 and other annexins are frequently deregulated in many cancers." (PMID 28754915, 2017). "In recent years debate has surround between ANXA1 expression and function in cancer." (PMID 29263330, 2017). "Therefore, the current study aimed to investigate the expression levels of miR-196a2, three of its putative targets; ANXA1, DFFA and PDCD4 mRNAs and annexin A1 protein in GI cancer tissue samples compared to cancer-free tissues." (PMID 29091952, 2017). "Notably, over-expression of ANXA1 and CAV1 has been associated with therapeutic resistance in different cancer settings." (PMID 27553366, 2016). "The role of ANXA1 in cancer progression is still discussed as this protein may have specific functions in different tumoral models." (PMID 26312765, 2015). "The protein was originally reported for its anti-phospholipase activity following glucocorticoid induction however, subsequent studies from our group and others showed that ANXA1 possesses a wide range of physiological and pathological functions, some of whom correlate to cancer development." (PMID 26312765, 2015). "Interestingly, a role for ANXA1 was identified during embryonic development and the proliferation-dependent processes of normal versus cancer cell differentiation although few evidences were reported about ANXA1 role in SC as well as in CSC biology." (PMID 26312765, 2015). "Numerous studies have demonstrated that the expression patterns of ANXA1 in cancers vary." (PMID 25695607, 2015). "To date, numerous reports have suggested differential expression of ANXA1 depending on cancer type: up-regulation in esophageal cancer, pancreatic cancer, skin squamous cell carcinoma, and colon cancer and down-regulation in cervical cancer, oral squamous cell carcinoma, and prostate cancer." (PMID 26000884, 2015). "As LPA can promote cancer cell migration during metastasis, we investigated whether this lipid could mediate the chemotactic actions of ANXA1." (PMID 26101324, 2015). "In a series of 135 cancer cases, they also found no specific association between ER, PR and Her2/neu expression and annexin A1 levels." (PMID 26000884, 2015). "However, the exact mechanisms through which ANXA1 exerts some or all of its effects, particularly in cancer, are still not clearly understood." (PMID 25481874, 2015). "DU145R80 cells showed both enrichment of ANXA1 protein in cell actin-rich regions and extracellularly (cell surfaces and supernatants) and these sub-cellular localizations had been consistently described to stimulate cancer cell invasion and metastasis." (PMID 26312765, 2015).
cancer (continued). "The discrepancy in these studies indicates that the effects of ANXA1 on cancer cells may be cell-type specific and that factors other than the expression level may affect its function." (PMID 25490767, 2014). "This suggests that ANXA1 influences cancer progression in different ways and that it may have different sub-cellular localizations that determine its functions." (PMID 25510623, 2014). "Interestingly, other studies in cancers that originate from multistep processes also show alterations in the AnxA1 expression, both in precursor lesions and carcinoma, indicating a greater proximity between precancerous and cancerous stages." (PMID 24719523, 2014). "Various types of cancers induce a differential expression of ANXA1." (PMID 24782913, 2014). "As it is known that ANXA1 plays a role in normal cell migration and in cancer cell invasion and metastasis, we also analyzed by confocal microscopy ANXA1 localization in the cellular motility structures identified by using focal adhesion kinase (FAK) or F-actin staining." (PMID 25510623, 2014). "The role of ANXA1 in cancer progression is still discussed; this protein may have specific functions in different tumoral models." (PMID 25510623, 2014). "It has also been suggested that the ANXA1 expression may differ in several types of cancer due to hormonal influence." (PMID 23431236, 2013). "These evidences suggest that Anxa1 has different role in different type cancers." (PMID 23991102, 2013). "Therefore, interference with the suppressive function of annexin A1 is likely to be a promising approach for novel anti-cancer therapies in the future." (PMID 23638088, 2013). "Other types of cancer in which the expression of annexin A1 has been shown to be altered include pancreatic adenocarcinoma, where it was found to show increased expression in the majority of tumours, renal cell carcinoma, prostate adenocarcinoma, breast cancer and B-cell non-Hodgkin's lymphoma." (PMID 18071363, 2008). "However, ANXA1 serum values are variable in different cancer types, including CRC." (PMID 41283264, 2025). "Moreover, ANXA1 plays a central role in the modulation of the immune response in cancer." (PMID 41283264, 2025). "Moreover, ANXA1 inhibition may enhance the anti-cancer efficacy of bortezomib—a key therapeutic agent in multiple myeloma (MM)—in both in vivo and in vitro models." (PMID 41283264, 2025). "It will be interesting to investigate how ANXA1 functions as a double-edged sword for cancer cells, and whether this phenomenon is true for other cell death-inducing/inhibiting cytokines and signaling exosomal proteins in other types of cellular stress/cell death conditions." (PMID 40520087, 2025). "Furthermore, a First-In-Human study evaluating the safety and tolerability of MDX-124 alone and in combination with anti-cancer therapies has recently been initiated in patients with locally advanced, unresectable or metastatic solid malignancies known to overexpress ANXA1." (PMID 38200229, 2024). "Loosing ANXA1 may lead to cancer cell resistance to apoptosis induced by chemotherapeutic agents." (PMID 38892394, 2024). "Interestingly, several cancer-related pathways were also enriched in the high ANXA1 group." (PMID 37735492, 2023). "Evidence has also indicated that ANXA1 could be a useful biomarker in certain forms of cancer." (PMID 35146757, 2022). "It remains to be determined whether ANXA1 plays a dominant role in certain cancers." (PMID 35146757, 2022). "Additionally, ANXA1 localization in the nucleus, cytoplasm and membrane could also be a clinical factor determining ANXA1 roles and regulatory mechanisms in cancer." (PMID 35770335, 2022). "Indeed, post‐translational phosphorylation is required for transfer of ANXA1 across the membrane, which could account for alterations in surface expression seen on different cells and in different cancers." (PMID 35146757, 2022). "This has not been previously reported and may explain the multiple functions of ANXA1 in cancer." (PMID 35664067, 2022).
cancer (continued). "Indeed, MVs containing AnxA1 of both normal and cancer cells can alter immune cells’ phenotype." (PMID 34571894, 2021). "In addition, it has been described that AnxA1 induces STAT3 activation in cancer." (PMID 34571894, 2021). "In addition, a clear interaction between ANXA2 and ANXA1 has been observed, which suggested that these two proteins might work together to promote the rapid proliferation of cancer cells." (PMID 32351780, 2020). "Thus, the aim of this paper is to systematically review and critically analyse 18 studies (in-vivo and in-vitro) to consolidate, in a concerted manner, all the information on differential expression of Annexin A1 in different types of cancer and the role this protein plays in tumorigenesis." (PMID 32823805, 2020). "On the other hand, the overexpression of this molecule has been reported in many cancers, although its clinical meaning is still controversial, which could be, in part, due to the localization of ANXA1 in the nuclear and cytoplasmic compartments, and also associated to the membrane." (PMID 31970082, 2019). "Moreover, ANXA1 has multiple functional roles in promoting cancer phenotypes." (PMID 31882967, 2019). "Furthermore, mRNA levels of annexin A1 and S100-A11 positively correlated in 1,072 comprehensively characterized human cancer cell lines from the Cancer Cell Line Encyclopedia data set, confirming that this association is also relevant for cancer types other than colorectal." (PMID 31545917, 2019). "Although CatD’s association with cancer is well known, this protein is not explored so far as a protease that could act in AnxA1 cleavage and we proved that this event is crucial for TNBC cell aggressiveness." (PMID 30884823, 2019). "Interestingly, the increased expression of cleaved AnxA1 reported in tumor cell lines and solid tumors suggests that this cleavage may be essential for maintenance of cancer aggressiveness." (PMID 30884823, 2019). "Notably, in the field of cancer, the EV pathway may represent the main mechanism of ANXA1 externalization, evolving through the exocytosis of microvesicles by fusion of multivesicular endosomes with the plasma membrane." (PMID 30518142, 2018). "Therefore, in this study, we investigated if ANXA1 could regulate miRNAs, and if these miRs could target certain factors of NF-κB pathway and modulate NF-κB activity and downstream function in cancer cells." (PMID 25536365, 2014). "Besides this validation of previous results in PTC, we performed a further evaluation of the levels of ANXA1 in a subset of pre-surgical FNAs suspicious for follicular neoplasm and suspicious for malignancy that had a diagnosis of cancer after histological examination." (PMID 24023790, 2013). "Thus far, the role of annexin A1 as a prognostic factor in cancer remains ambiguous." (PMID 22929401, 2012). "The fact that this protein also contains phosphorylation sites that can be phosphorylated by a number of proliferative signaling molecules, including PKC and EGF receptor tyrosine kinase, suggests that AnxA1 may also have a role in signaling pathways that are important in cancer." (PMID 23230437, 2012). "Spatial transcriptome analysis and immunohistochemical staining revealed upregulation of annexin A1 (ANXA1), a calcium-dependent phospholipid-binding protein involved in inflammation and cancer progression, in the early resistance group." (PMID 41529251, 2026). "Thereby, the autocrine AnxA1/FPR1 signaling promotes malignant abilities, migration, and proliferation of cancer cells." (PMID 41283264, 2025). "To comprehensively characterize the direct roles of ANXA1 in SCLC, we assessed in vitro endpoints of the malignant phenotype in cancer cell lines." (PMID 40361334, 2025). "Oxidative stress-induced exosomes derived from cancer cells induced apoptosis and inhibited inflammation in an ATE1-dependent manner which was mediated by the exosomal secretion of the ANXA1 cytokine." (PMID 40520087, 2025).
cancer (continued). "Prior studies have demonstrated that ANXA1 and MGP are up‐regulated in various cancers and facilitate cancer immune evasion." (PMID 41176774, 2025). "Functionally, decreased ANXA1 compensated for ESCC malignant proliferation, migration, and invasion induced by circNF1 knockdown, confirming that ESCC cells drive cancer development and metastasis by upregulating circNF1 to impair ANXA1 expression." (PMID 40158127, 2025). "Annexin A1 (ANXA1), a calcium-dependent phospholipid-binding protein, is considered a key modulator of cancer biology." (PMID 41283264, 2025). "In this study, we performed the comprehensive characterization of ANXA1 in SCLC, exploring its role in the TME, cancer cell growth, chemosensitivity, and gene expression." (PMID 40361334, 2025). "In our previous study, we found a notable release of HMGB1 and ANXA1 under low dose of TLC388, prompting ICD and enhancing cancer immunogenicity in vitro and in vivo." (PMID 38564022, 2024). "Then, we compared ANXA1 expression in 23 cancer cell lines among the 14 tumors, in which the GBM cancer cell lines exhibited a high ANXA1 expression." (PMID 37434432, 2023). "Then, we analyzed the upregulated top five differentially expressed genes between the paracancer tissue and the cancer tissue, which included LAMB3, FN1, KRT17, KRT19, and ANXA1." (PMID 35428170, 2022). "Anthracyclines, e.g., doxorubicin or mitoxantrone, affect cancer cells by enhancing the cell surface expression of calreticulin (CRT) followed by the release of high-mobility group box 1 (HMGB1), ATP, annexin A1, and type I interferon from cancer cells." (PMID 36679904, 2022). "Low-dose lipotecan not only damages cancer cells but also triggers ER stress for CRT surface exposure and HMGB1 and ANXA1 release, regarded as the characteristics of ICD induction." (PMID 33799527, 2021). "AnxA1 and its interaction with FPR receptors has potentially numerous therapeutic applications in the context of acute and chronic inflammation and cancer (Section 2.1, Section 2.2, Section 2.3 and Section 2.4)." (PMID 33810523, 2021). "Major DAMPs are ATP, calreticulin (CALR), high-mobility group box 1 (HMGB-1), type I interferon (IFN), annexin A1 (ANXA1), heat shock proteins 70 and 90 (HSP70, HSP90), or diverse nucleic acids, mainly cancer cell derived ones." (PMID 33947098, 2021). "Among the 24 potential genes, HSP90AA1, ANXA1, ARRDC4 and PSAT1 were involved with cancer progression." (PMID 34916487, 2021). "Secreted HMGB1 (ecto-HMGB1) and ANXA1 (ecto-ANXA1) were significantly detected at low doses of lipotecan in SW480 and CT26 cancer cell lines." (PMID 33799527, 2021). "The action of resveratrol led to the sensitization of cancer cells to the action of chemotherapeutic agents by influencing the expression of genes (ABCB1, ANXA1, TXN) and proteins (P-gp, annexin I, thioredoxin) related to the MDR process." (PMID 34299624, 2021). "Annexin A1 (ANXA1) and thioredoxin (TXN) are other possible mechanisms involved in MDR and consequently, cancer progression." (PMID 33478512, 2021). "Adding antibodies specific for two of these molecules, Annexin-A1 and CEACAM1, inhibited macrophage activation, supporting their role as cancer “danger signals” recognized by macrophages." (PMID 34712237, 2021). "ANXA1 was also found to be correlated with IGFBP2 (insulin-like growth factor-binding protein 2), a circulating biomarker for cancer diagnosis and a potential immunotherapeutic target, also belonging to the gene signature identified by Model II." (PMID 32070274, 2020). "Other molecules, such as annexin A1 (ANXA1) and cancer cell-derived nucleic acid, also function as DAMPs." (PMID 32992948, 2020). "The resulting heatmap showed that in the majority of malignancies, TILs were significantly correlated with multiple representative ICD mediators, such as CALR, LRP1, ANXA1, FPR1, TLR3, IFNAR1, PANX1, and P2RX7." (PMID 33299118, 2020).